IL1B (interleukin 1 beta)
Diseases named in the same sentence as IL1B in open-access papers (continued):
Sharing a sentence is not in itself a finding about the gene and the disease.
colitis (continued). "Previous studies described that inflammation of the colon increases the activity of inflammation-related cytokines including TNF-α, IL-1β, and IL-6 in serum and colon tissues in murine colitis." (PMID 34066160, 2021). "UAMC-00050 treatment also significantly decreased protein levels of TNF-α, IL-1β, IL-6 and IL-17 present in the colons of the colitis animals." (PMID 34248633, 2021). "Some proinflammatory cytokines and mediators (e.g., TNF-a, IL-6 and IL-1β) have been used as markers of anti-inflammatory activity in a dextran sodium sulfate colitis mouse model, and IL-10 has anti-inflammatory properties and functions in immune regulation." (PMID 34490398, 2021). "IL-1β is another pro-inflammatory cytokine secreted within the immune cell-infiltrated lamina propria during colitis." (PMID 33946346, 2021). "The levels of TNF-α, IL-1β, and IL-6 in colon tissues of colitis mice were elevated by contrast with those in the Model group." (PMID 34055024, 2021). "Using colon tissues from both UC patients and colitis mouse models, IL-1β-induced upregulation of miR-200c-3p decreased levels of occludin, which negatively impacted barrier function." (PMID 34943865, 2021). "TNF-α and IL-1β are potent inflammatory mediators, production of which is remarkably increased in the colon tissue of patients with colitis." (PMID 33995942, 2021). "On the other hand, caspase-1 (a key inflammasome component) deficiency resulted in limited IL-1β and IL-18 production associated with ameliorated inflammation in DSS-induced colitis." (PMID 33562334, 2021). "The total histology scores for colitis, as well as the colonic mRNA expressions of IL-1β, IL-6, and IL-10 were higher after the sympathectomy, compared to the sham." (PMID 34884737, 2021). "In this regard, studies on rats have found that sodium butyrate is effective in the topical treatment of TNBS (trinitrobenzene sulphonic acid)-induced colitis in mice, and significantly reduced serum IL-1β production." (PMID 34453080, 2021). "In the inflammatory phase of DSS-induced colitis, IL-1β, TNF-α and IL-6 mRNA expression were significantly increased in the colon." (PMID 34749758, 2021). "On the other hand, OA reportedly prevented colitis by inhibiting Th17 cells and the down-regulation of the expression of interleukin IL-1β, NF-κB, MAPK, and RORγt in the colon." (PMID 34360922, 2021). "BTK-deficient mice show increased DSS- or 2,4,6-trinitrobenzene sulfonic acid (TNBS)-induced colitis, which can be ameliorated by administration of IL-1β monoclonal antibody." (PMID 33808793, 2021). "In contrast to the results reported by Tye and colleagues, the Williams laboratory observed that both IL‐1β and IL‐18 are responsible for the attenuation of colitis." (PMID 34705319, 2021). "Here, we have designed this study to investigate the therapeutic effects of IL-1β-primed ERCs in the attenuation of experimental colitis." (PMID 34090510, 2021). "High levels of pro-inflammatory cytokines, such as TNF-α, IL-1β, and IL-12, are associated with DSS-induced colitis in mice." (PMID 34899643, 2021). "Due to its potent anti-inflammatory effect, rosmarinic acid has been used in the treatment of inflammatory diseases such as arthritis, colitis, rhinitis, and acute pancreatitis through inhibition of cytokines including NFκB, IL1b, and IL8." (PMID 34072744, 2021). "Results demonstrated that feeding BLIDF markedly mitigated DSS-induced acute colitis symptoms and down-regulated IL-6, TNF-α, and IL-1β levels in the colon and serum of colitis mice." (PMID 33807544, 2021). "In accordance with other studies, we showed that colitis induction resulted in a significant increase in the level of proinflammatory cytokines (IL-1β, TNF-α, IL-6, and IFN-γ) and decreased the anti-inflammatory cytokine IL-10 in colon tissue." (PMID 33995942, 2021).
colitis (continued). "A further study showed that TpH2−/− mice with DSS-induced colitis had increased severity of disease characterized by an increased secretion of the pro-inflammatory cytokines IL-1β, IL-6 and, TNF-α, and high mortality rates in comparison to the wild type." (PMID 34502396, 2021). "The authors further verified that the administration of micheliolide strongly inhibited IL-6, TNF-α, and IL-1β expression in a murine model of DSS-induced colitis." (PMID 34208907, 2021). "DHPP treatment improved DSS-induced colitis symptoms in rats and lowered the expression of IL-1β, IL-8, and TNF-α." (PMID 34073220, 2021). "In the next phase of the in vitro studies, we used cells of intestinal epithelial origin (Caco-2) and mimicked the conditions that occur in the intestinal microenvironment during colitis by addition of TNFα, IL1-β, INFγ, and LPS." (PMID 34444876, 2021). "The same result was observed in HTR7−/− mice post-DSS-induced colitis, in which IL-1β was upregulated." (PMID 34502396, 2021). "It has been reported that DSS-induced colitis can promote the release of proinflammatory mediators.Therefore, the serum levels of IL-18 and IL-1β were detected by ELISA, which were prominently increased in the UC group compared with the control group." (PMID 34394827, 2021). "Together, PTPN2 plays an inhibitory role in the development of colitis by regulating inflammasome activation and IL-1β production." (PMID 33808793, 2021). "Colon Tnf expression was 4.6 fold higher, and, strikingly, Il1b expression was 1419-fold higher in DSS-treated WT mice compared to 12-week old IL-10KO mice with colitis." (PMID 33953267, 2021). "Mice deficient in Il1a were more resistant to DSS colitis, whereas Il1b−/− mice had more severe colitis and impaired tissue repair capacity compared to wild-type (WT) mice." (PMID 33562334, 2021). "The relative gene expression of pro-inflammatory marker IL1β was higher in all groups of rats with colitis in comparison to the HA group, but this difference was only significant for the AC group (p < 0.01)." (PMID 33499240, 2021). "Oral administration of PCA improved symptoms of DSS-induced colitis in rats and prevented the increase in the pro-inflammatory cytokines IL-1β, IL-6, and TNF-α that was seen in controls." (PMID 34073220, 2021). "In a mouse model of colitis, IL-1β was shown to be involved in mediating tissue repair during resolution of colitis." (PMID 34759934, 2021). "The main cellular mechanism of Res resistance to dextran sodium-sulphate-induced colitis is achieved by down-regulating the expression of inflammatory molecules such as IL-6, IL-1β, IFN-α and TNF-α." (PMID 34944291, 2021). "Compared with the mice in the sham group, an ELISA revealed that pro-inflammatory cytokine levels, including those of TNF-α, IL-1β, and IL-6, increased significantly in the murine model of colitis." (PMID 34594215, 2021). "Given together, it indicated that treatment of IL-1β-primed ERCs effectively reduced intra-colon M1 cell infiltration, but increased M2 cell infiltration in this colitis model." (PMID 34090510, 2021). "The experiment was conducted on a dextran sodium sulfate (DSS) colitis mice model, in which an increase in colonic IL1β concentration was observed relative to control mice." (PMID 34298967, 2021). "Those researchers found that rats receiving orally administrated propolis extract for 1 week prior to 3% DSS treatment showed decreased colitis and reduced inflammatory cytokine (IL-1β, IL-6, and MCP-1) levels." (PMID 32788877, 2020). "The plant-derived alkaloid N-methylcytisine and the tea alkaloid theophylline mitigate colitis by downregulating TNFα, IL-1β, and IL-6 expression in DSS and acetic acid models of colitis, respectively." (PMID 32855621, 2020). "In a 2,4,6-trinitrobenzenesulphonic acid induced rat colitis model, the aqueous extract of P. edulis leaves reduced pro-inflammatory levels of IL-1β and TNF-α." (PMID 32508631, 2020).
colitis (continued). "We previously reported that the expression level of IL-1β in the colonic mucosa was positively correlated with the disease severity of DSS-induced colitis in mice." (PMID 33192516, 2020). "Oral supplementation with 2-fucosyllactose significantly decreased the severity of colitis in IL-10−/− mice, reducing the expression of IL-1β and IL-6 and increasing TGF-β expression and expansion of the propionate-producing commensal Ruminococcus gnavus." (PMID 32429359, 2020). "We found that the severe inflammation that develops in Mbd2−/− mice during DSS driven colitis is accompanied by a large accumulation of IL-1β+ monocytes." (PMID 32117307, 2020). "In conclusion, NK109 alleviated neuropsychiatric disorders and colitis by modulating IL-1β expression, gut microbiota, and vagus nerve-mediated gut–brain signaling." (PMID 33182607, 2020). "It has been shown that the levels of TNF-α, IL6, and IL1β were significantly increased in mice with colitis induced by saline in in vivo studies." (PMID 32265719, 2020). "These components acted to protect mice against colitis inflammation by significantly suppressing cytokines [γ‐interferon (IFNγ), IL‐6,IL‐1β, and IL‐17a] related to colitis pathology and upregulating anti‐inflammatory cytokine IL‐10." (PMID 32410383, 2020). "Following treatment with 10 mg/kg and 50 mg/kg sinapic acid, the protein levels of NLRP3, ASC, IL-1β, and caspase-1 were reduced in colitis mice." (PMID 33312339, 2020). "Study reveals that APS (200 mg/kg) treatment increases weight and colon length and reduces NF-κB DNA phosphorylation activity and down-regulates TNF-α, IL-1β, IL-6, IL-17 expressions associated with improvement in DSS-induced mice colitis." (PMID 32063999, 2020). "A recent study identified the dual role for PTPN2 in directly regulating inflammasome activation and IL‐1β production to suppress pro‐inflammatory responses during colitis but promote intestinal tumor development." (PMID 32207560, 2020). "The production of TNF-α, IL-1β, and IL-6 plays leading roles in the initiation and progression of colitis, and some of them have been regarded as a logical target for IBD therapy." (PMID 33363184, 2020). "On the other hand, recent findings have suggested that increased IL-1β production plays a protective role against colitis." (PMID 33143375, 2020). "Meanwhile, the characteristics of colitis coupled with many other chronic inflammatory diseases are characterized with the production of more pro-inflammatory cytokines such as IL-6, IL-1β, and TNF-α in serum and tissue." (PMID 32670051, 2020). "Negative regulatory effects of GMP on IL-1β gene expression have been reported in other intestinal disease experimental models, such as ileitis and colitis." (PMID 32443501, 2020). "Further, oral administration of 6-shogaol, a representative active component of ginger, showed protective effects by regulating pro-inflammatory factors such as iNOS, TNF-α and IL-1β in dextran sulfate sodium-induced colitis and aspirin-induced gastric ulcer." (PMID 33066164, 2020). "In the present study, increased production of iNOS, COX-2, IL-6, TNF-α, and IL-1β was observed in mice with DSS-induced colitis." (PMID 33536931, 2020). "Here, we found that DSS significantly increased the serum and colonic levels of IL-1β and IL-18 in colitis mice." (PMID 33312339, 2020). "SSP and 5-ASA significantly reduced IL-1β, IL-4, IL-9, and IL-17A concentrations in the colitis mice, followed by lower expression of the CD11c+CD103+E-cadherin+ and CD11c+CD103+TNF-α+ cells." (PMID 32754049, 2020). "Elevated levels of TNF-α, IL-1β, and IFNγ due to activation of immune cells are hallmarks of colitis, in both humans and mice." (PMID 32377161, 2020). "In fact, inhibition in the production of TLR-4, NF-κB p65, COX-2, IL-17, TNF-α, IL-1β, and IL-6 is considered useful in treating colitis." (PMID 32848723, 2020).
colitis (continued). "Intrarectal treatment of colitis with 30 mg/kg chitosan alone and with 30 mg/kg 5-ASA for 3 days led to a significant decrease in MPO, ALP, TNF-α, IL-6, IL-1β and NF-κB in colitis mice compared to untreated mice." (PMID 33138176, 2020). "In contrast, mice treated with BtLj displayed attenuated colitis, accompanied by a significant reduction in IL-1β and an increase in IL-10 transcripts." (PMID 32661259, 2020). "The mRNA expression level of Cxcl2 and Il-1β in the colons of WT colitis mice was markedly elevated on day 7 (Cxcl2; 0.0 ± 0.0 in WT normal, 5.3 ± 1.7 in WT colitis; p < 0.01, Il-1β; 0.4 ± 0.1 in WT normal, 6.6 ± 2.1 in WT colitis; p < 0.01)." (PMID 33192516, 2020). "Drinking water with soybean-derived tripeptide VPY can reduce DAI, weight loss, MPO activity, and expressions of IL-1β, IL-6, IL-17, IFN-γ, and TNF-α in colitis mice, suggesting that VPY can treat IBD." (PMID 32963495, 2020). "The subsequent induction and expression of various inflammatory cytokines (TNF-α, IL-6, IL1β, IL-17, and IFN-γ) and enzymes (iNOS and COX-2) that are associated with the initiation and development of colitis 49, 79 were also prevented by low-dose IL-2." (PMID 32308767, 2020). "Blocking the activation of IL-1β attenuates the symptoms of DSS-induced colitis and reduces IL-6 gene expression." (PMID 33312339, 2020). "NLRP3 KO mice were found to be susceptible to DSS- and 2,4,6-trinitrobenezene sulfonic acid-induced experimental colitis and had reduced levels of IL-1β, IL-10, and TGF-β." (PMID 33143375, 2020). "It was reported that the occurrence of colitis is associated with the secretion of IL-1β and IL-18, our data also demonstrated that secretion of IL-1β and IL-18 increased in colitis mice colon." (PMID 33240089, 2020). "IL-23A-responsive ILCs were also found to mediate intestinal pathology in a murine colitis model, and IL-1β-responsive IL-17A-producing ILCs have been reported in the conjunctiva." (PMID 31964744, 2020). "The γδT cells, purified from the spleens of normal mice, were activated by stimulation with IL-1β and IL-23, and were then adoptively transferred to mice with colitis." (PMID 32929062, 2020). "Rats with colitis displayed a significant increase in colonic IL-1β levels (196.1 ± 36.3 ng/mg tissue) compared to the control animals (45.9 ± 21 ng/mg tissue)." (PMID 32575844, 2020). "As with the previously reported effect of melatonin on DSS- or TNBS-induced colitis, melatonin suppresses potent pro-inflammatory mediators in colitis such as Il1b and Il17a, and controls microbiota in the intestine." (PMID 32042047, 2020). "DSS treatment significantly induced increases in the protein levels of NLRP3, ASC, IL-1β, and caspase-1 in the colons of the colitis mice." (PMID 33312339, 2020). "Shaoyao decoction decreases the expression of TNF-α, IL-1β, and IL-6 in DSS-induced colitis-associated CRC." (PMID 32565784, 2020). "Mbd2−/− mice displayed dramatically worse pathology than wild type controls during dextran sulfate sodium (DSS) induced colitis, with increased inflammatory (IL-1β+) monocytes." (PMID 32117307, 2020). "In a dextran sodium sulphate caused mice colitis model, P. edulis peel flour reduced pro-inflammatory cytokine TNF-α, IL-1β, IL-6, IL-12, and IL-17 expression and decreased the expression of MCP-1 and ICAM-1." (PMID 32508631, 2020). "As DSS-induced colitis-like symptoms are reportedly accompanied by upregulation of pro-inflammatory cytokines, the plasma levels of IL-6, IL-1β, and TNF-α were examined." (PMID 32708415, 2020). "In the present study, the infiltration of neutrophils and the upregulation of CXCL2 and IL-1β observed in colonic tissues of colitis mice were significantly suppressed in the IL-4Rα-/- mice." (PMID 33192516, 2020). "As typical indicators of inflammatory DCs, the levels of CD11c+CD103+E-cadherin+ cells and pro-inflammatory cytokines [interleukin (IL)-1β, -4, -9, and -17A] were decreased in mice with colitis treated by SSP for 10 days." (PMID 32754049, 2020).
colitis (continued). "Demethyleneberberine, tetrandrine, and norisoboldine show protective effects in the DSS colitis model and reduce the levels of colonic IL-1β, TNFα, and phosphorylated NF-κB p65 subunit." (PMID 32855621, 2020). "During the acute phase of colitis, plasma levels of IL-6 are increased, accompanied by activation of microglia, as well as increased levels of IL-1β, TNF-α, and p21 in the hippocampus." (PMID 32047521, 2020). "Since the activation of caspase‐4/11 eventually leads to IL‐1β production, which plays a pivotal role in regulating innate‐immune responses and the homeostasis of colon epithelial cells, GPx8 deficiency may cause increased inflammation and high susceptibility to colitis." (PMID 31782617, 2020). "Further experimental validation revealed that CSCC attenuated DSS-induced colitis by the suppression of the mRNA levels of IL-17A and of the cytokines it induces, such as IL-6, IL-1β, and TNF-α." (PMID 32382313, 2020). "IL-1β protein levels were increased in IL-10 KO mice, but a caspase-1 inhibitor significantly improved spontaneous colitis in these mice." (PMID 33143375, 2020). "For instance, green tea-derived polyphenol AcEGCG can protect against DSS-induced colitis by decreasing IL-1β, IL-6, TNF-α, and COX-2 productions and reducing NF-κB (p65 and IκBα) phosphorylation." (PMID 33664740, 2020). "The level of pro-inflammatory cytokines (TNFα, IL-1β and IL-6) in the blood serum, as well as IL-1β in the colon tissue of mice with colitis receiving algae extract, was lower than that of control animals (pronounced manifestations of colitis)." (PMID 32486405, 2020). "Recently, we observed after colitis development and C. glabrata challenge a high production of IL-6 and IL-1β, which are highly important in the recruitment of neutrophils and macrophages into the inflammatory site." (PMID 30646601, 2019). "GA attenuates experimental colitis by suppressing IL-6, IL-1β, TNF-α, IL-17 and IFN-γ production and inhibiting p65-NF-κB and IL-6/p-STAT3 (Y705) activation." (PMID 31026283, 2019). "Consistently, we observed an elevation of these cytokines, including TNF-α, IL-1β, and IL-6, p-IκB, NFκB p65, p22-phox, gp91-phox, and Keap1 in colitis mice." (PMID 31827675, 2019). "In the rat colitis model, IL-1β, IL-6, and IL-17 have been recognized as important proinflammatory cytokines in the course of UC, and overexpression of these cytokines is related to activation of the NF-κB and MAPK pathways in colonic tissue." (PMID 31920656, 2019). "The mRNA fold of IL-1β was also detected because of its important role in proinflammatory cytokines in colitis." (PMID 31182999, 2019). "Anti-IL-1β treated mice had also gained significant weight without colon thickening and shortening as macroscopic signs of colitis." (PMID 30653608, 2019). "A common feature of this acute colitis is the massive infiltration of innate immune cells that produce large amounts of pro-inflammatory mediators such as TNFα, IL-6, IL-1β, IL-23 and GMCSF." (PMID 31189465, 2019). "Several lines of evidence suggested that IL-1β-dependent activation of IL-1 receptor (IL-1R) in gut-infiltrating immune cells have crucially important role in the development of colon inflammation during the onset of DSS-induced colitis." (PMID 31336879, 2019). "Exposure to even low doses of Al (1.5 mg/kg) has been shown to aggravate intestinal damage in mouse colitis models, such as worsening of colitis and upregulation of the mRNA expression of inflammatory cytokines IL1β, IL17A, and Nlrp3." (PMID 31523502, 2019). "Colitis induction increased serum IL-6, TNF-α, and IL-1β by 5-, 4.25-, and 1.9-fold, respectively in AA-colitis group in comparison to the NC group." (PMID 34466462, 2019). "To evaluate the anti-inflammatory effects of PWS on DSS + CD-induced colitis, we focused on the pro-inflammatory cytokine IL-1β, and the anti-inflammatory cytokines IL-10 and TGF-β." (PMID 31888274, 2019).